SAA1 (serum amyloid A1)
Diseases named in the same sentence as SAA1 in open-access papers (continued):
Sharing a sentence is not in itself a finding about the gene and the disease.
cancer (continued). "All these reports indicate collectively that SAA1 fragments are indeed cancer-stage-specific but not cancer-type-specific components of cancer peptide signatures." (PMID 22900176, 2012). "CCNE1 and SAA1 have not been previously implicated in RCC, but are implicated in other cancers." (PMID 32986937, 2020). "Upregulation of 48 proteins in samples of cancer patients was reported, that included several inflammation/acute phase-related proteins: A1AG1 (ORM1), A1AT (SERPINA1), AACT (SERPINA3), CO4B, CO9, HPT, ITIH4, LBP and SAA1, which upregulation was revealed also in our study." (PMID 26376850, 2015). "Other proteins, such as CLEC3B, ITIH4, SAA1, and C20ORF3 exhibited increased expression in cancer EVs, while RBP4, SAA1, and DBP did not exhibit significant differences between normal and cancer samples." (PMID 33808296, 2021). "The expression of RBP4, SAA1, and DBP in cancer EVs was not significantly altered, compared to that in normal EVs." (PMID 33808296, 2021).
bacterial infection (10 papers, 2014 to 2025). "In a more recent study, the investigators used Saa TKO mice (triple knockout of the mouse Saa1, Saa2 and Saa3) to demonstrate that these mice were more susceptible than the wild-type controls to bacterial infection as they succumbed to different ways of bacterial infections." (PMID 39940756, 2025). "Elevated plasma levels of SAA1 is a well-documented clinical indicator for inflammatory conditions, and is suggested to have a role in host defense against bacterial infection." (PMID 32010199, 2019). "We successfully present the use of a LDW-patterned multi-path LFD for multiplexed detection of a biomarker panel comprising C-reactive protein (CRP) and Serum amyloid A-1 (SAA1), used for the diagnosis of bacterial infections." (PMID 30347807, 2018). "We successfully demonstrate the use of these LDW-fabricated multi-path LFDs for simultaneous detection of a biomarker panel comprising C-reactive protein (CRP) and Serum amyloid A-1 (SAA1), commonly used for the diagnosis of bacterial infections." (PMID 30347807, 2018). "As a proof of principle, we have shown the successful use of a dual-channel LFD for multiplexed detection of a biomarker panel comprising CRP and SAA1, used commonly for the diagnosis of bacterial infections." (PMID 30347807, 2018). "We find that Saa1/2−/− mice, which harbor deletions of both the Saa1 and Saa2 genes, have higher bacterial burdens in spleen and liver following an acute bacterial infection, supporting an essential role for SAAs in the response to microbial challenge." (PMID 25073702, 2014). "Similarly, IL-6 induces rapid SAA1 synthesis, which is a more sensitive early marker of bacterial infection than CRP, often increasing over 1000-fold." (PMID 40572197, 2025). "Given that acute-phase proteins typically increase during early bacterial infections, we measured CRP and SAA1 levels in BALF by ELISA." (PMID 40572197, 2025). "To examine the expression patterns of SAA isoforms under different inflammatory conditions, we measured SAA1, SAA2, SAA3, and SAA4 levels in SAA+/+ mice across three experimental groups: healthy controls, LPS-treated (sterile inflammation), and P. aeruginosa-infected (bacterial infection)." (PMID 40061939, 2025).
cardiovascular disease (10 papers, 2011 to 2026). "Other biomarkers associated with cardiovascular disease risk include the acute phase protein serum amyloid A1 (SAA1) and the antioxidant protein serum paraoxonase/arylesterase 1 (PON1), both situated on high-density lipoprotein as well." (PMID 38054074, 2023). "A recent review concluded that even small increases of SAA1 levels are associated with an increased risk of cardiovascular disease and that such increases have been shown for other occupational exposures." (PMID 33735215, 2021). "Directly after weight loss, SAA1 and CRP, two prominent risk markers for cardiovascular disease, showed median decreases of 43% and 35%, respectively." (PMID 28007936, 2016). "Additionally, both proteins are associated with increased risk for cardiovascular diseases (CVD), where an increase of 10% of CRP levels leads to a 5.5% increase in CVD risk and a twofold increase of SAA1 to a 17% increase." (PMID 28007936, 2016).
metabolic disease (6 papers, 2008 to 2025). A congenital disorder (due to inherited enzyme abnormality) or acquired (due to failure of a metabolically important organ) disorder resulting from an abnormal metabolic process. "While much prior work has focused on the hepatic acute-phase SAA1 and SAA2 subtypes, important roles for extra-hepatic SAA in the chronic inflammatory processes associated with metabolic diseases are now emerging." (PMID 37396595, 2023). "This is in contrast to recentlypublished human studies which reported thatthe elevation of plasma A-SAA in metabolic disease is linked toinduction of Saa1 and Saa2 in adiposetissue but apparently not in liver." (PMID 18584041, 2008).
kidney diseases (4 papers, 2019 to 2025). "For CKF, it was found that SAA1 concentration in serum of patients with kidney diseases was elevated." (PMID 37510279, 2023). "We identified six genes enriched to kidney diseases and ccRCC (AR, DPP6, GNB3, IL4, SAA1, SEMA3G)." (PMID 35565241, 2022).
infectious disease (2 papers, 2012 to 2021). A disorder directly resulting from the presence and activity of a microbial, viral, or parasitic agent in humans. "Previous studies reported that Saa1 could activate and recruit neutrophils to the lung in infectious diseases." (PMID 34566982, 2021).
hematological malignancies (1 paper, 2025). "In addition, researchers have developed blocking monoclonal antibodies against SAA1 as promising novel targets for the treatment of hematological malignancies to inhibit SAA1’s potent oncogenic effects on malignant HSCs and to examine its potential therapeutic activity." (PMID 40299483, 2025).
immune disorders (1 paper, 2020). "We also verified this finding in the plasma and the liver tissues of patients with AIH, suggesting that SAA1 may indeed be involved in immune disorders associated with AIH." (PMID 31906950, 2020).
neurodegenerative disease (1 paper, 2013). A disorder of the central nervous system characterized by gradual and progressive loss of neural tissue and neurologic function. "While Necab3, Apbb2, App, Psen1, Prkcg and Saa1 are associated with Aβ accumulation, Park2 and Snca are associated with protein aggregation in AD and PD, as well as other neurodegenerative diseases." (PMID 24278249, 2013).
respiratory diseases (1 paper, 2020). "Receiver operating characteristics analyses using a 5-protein panel (CFHR5, LRG1, CRP, LBP, and SAA1) exhibited discriminatory power in distinguishing TB from other respiratory diseases (AUC = 0.81)." (PMID 32780727, 2020).
SAA1 also shares sentences with these, for which no sentence is quoted: chronic kidney disease (3 papers); AL amyloidosis (2); alkaptonuria (2); cardiomyopathy (2); experimental autoimmune encephalomyelitis (2); familial Mediterranean fever (2); gastrointestinal infections (2); heart failure (2); Kawasaki disease (2); metabolic dysfunction-associated steatotic liver disease (2); metabolic syndrome (2); oligodendroglioma (2); osteosarcoma (2); thrombosis (2); abortion (1); acute coronary syndrome (1); acute lung injury (1); adenocarcinoma (1); alcoholic steatohepatitis (1); anaplastic astrocytoma (1); atopic dermatitis (1); atrioventricular block (1); Atrophy (1); autoimmune thyroid disease (1); autosomal dominant hereditary pancreatitis (1); bacterial pneumonia (1); bladder cancers (1); brain tumors (1); bronchiectasis (1); bronchopneumonia (1).
A further 48 diseases each share a sentence with SAA1 in 1 paper.